DKK1 (dickkopf Wnt signaling pathway inhibitor 1)
Diseases named in the same sentence as DKK1 in open-access papers (continued):
Sharing a sentence is not in itself a finding about the gene and the disease.
breast carcinoma (continued). "Finally, DKK1 has become a relevant candidate target for immunotherapeutic approaches to different cancers, and it may also have potential in a preventive vaccination strategy for women at high risk of developing breast cancer." (PMID 17245340, 2007). "Similarly, DKK1 neutralization significantly reduced the growth of the luminal B, ER+/PR+, hormone-sensitive E0771 breast cancer cell line." (PMID 39885132, 2025). "Recent studies 77 have highlighted DKK1 as a marker of immune cell populations that may contribute to a promoting TME by inhibiting NK cell activation in breast cancer." (PMID 40303301, 2025). "In addition, CAFs promote breast cancer bone metastasis by inhibiting NK cell activation and function through dickkopf-related protein 1 (DKK1)." (PMID 40038745, 2025). "Breast cancer cells frequently release Wnt inhibitors like DKK-1 and SOST." (PMID 40426987, 2025). "Finally, increased DKK1 levels and reduced cytotoxic NK cells are also detected in breast cancer patients with progressive bone disease." (PMID 39885132, 2025). "While the source of DKK1 in these patients is unknown, the low expression of DKK1 in the ER+ tumors by IHC and scRNAseq suggests that bone might be the primary site for DKK1 production in ER+ breast cancer." (PMID 39885132, 2025). "In this study, we demonstrate that high levels of DKK1 in breast cancer create an immune suppressive microenvironment through direct inhibition of NK cell effector functions, and targeting DKK1 has significant anti-tumor effects in the primary and metastatic settings." (PMID 39885132, 2025). "Importantly, increased DKK1 levels and reduced cytotoxic NK cells are detected in women with progressive breast cancer." (PMID 39885132, 2025). "Moreover, this study demonstrates the previously unappreciated impact of DKK1 on systemic and local immune suppression in breast cancer." (PMID 38659818, 2024). "Importantly, increased DKK1 levels and a reduced number of cytotoxic NK cells are also detected in breast cancer patients with progressive disease." (PMID 38659818, 2024). "However, there were relatively few studies to show the patient-relevance of DKK1 expression in ER+ breast cancers." (PMID 38978585, 2024). "Importantly, we find that DKK1 is significantly enriched in ER+ breast cancer plasma compared to healthy controls." (PMID 38978585, 2024). "Meanwhile, the H3K27ac of four common cancers, K562 (bone cancer), HCC827 (lung cancer), T24 (bladder cancer), and CAL51 (breast cancer), were visualized, had low H3K27ac levels at the DKK1-SE regions, demonstrating that histone modification information in this region is not widespread." (PMID 39107271, 2024). "In breast cancer, DKK1 is amplified in the serum of breast cancer patients with bone metastases." (PMID 38978585, 2024). "The secretory glycoprotein DKK1 has been found to exhibit elevated serum levels in various cancers, including liver cancer, pancreatic cancer, lung cancer, esophageal cancer, gastric cancer, prostate cancer, kidney cancer, breast cancer, cervical cancer." (PMID 39107271, 2024). "Interestingly, it has been shown that MEX3A regulates the Wnt pathway by downregulating Dickkopf WNT signaling pathway inhibitor 1 (DKK1) expression in breast cancer." (PMID 38914858, 2024). "In breast cancer, DKK1 protein expression is enhanced in breast cancer vasculature compared to normal breast tissue, and in a xenograft mouse model of breast cancer, recombinant DKK1 promotes angiogenesis and tumor growth." (PMID 39107271, 2024). "Importantly, increased DKK1 levels and reduced number of cytotoxic NK cells are detected in breast cancer patients with progressive bone metastases compared to those with stable disease." (PMID 38659818, 2024). "DKK1 protein expression was determined in a cohort of early-stage breast cancer patients." (PMID 38036593, 2023).
breast carcinoma (continued). "In cancer, the role of DKK-1 is complex, with a growing body of evidence showing that it can either inhibit cancer metastases in ovarian cancer and colorectal cancer or promote cancer progression in osteosarcoma, breast cancer, and prostate cancer." (PMID 38067123, 2023). "This analysis indicates that the predicted PTB-related genes including ICAM1, CRHBP, PLAGL1, EGR2, CNTLN, and DKK1 play an important role in preforming biological activities associated with PTB, infant disease, and possibly breast cancer, due to the gestational age-induced." (PMID 36788602, 2023). "We previously identified DKK1 and GRB7 as genes with linked expression using Artificial Neural Network (ANN) analysis; here, we determine protein expression in a large cohort of early-stage breast cancer patients." (PMID 38036593, 2023). "Furthermore, gene set enrichment analysis (GSEA) suggested that breast cancer patients with higher DKK1 levels showed lower enrichment of lipid peroxisomal metabolism associated genes." (PMID 35296660, 2022). "Likewise, DKK1 was identified as a direct target of miR-372 and miR-373 in breast cancer and CRC cells, and knockdown of DKK1 promoted the growth and invasive activity of cancer cells." (PMID 35355709, 2022). "Depending on the tumor type, Dkk1 upregulation has a conflicting roleDkk1 overexpression is involved in the invasiveness of pancreatic ductal adenocarcinoma, while in breast cancer, it is responsible for the lower proliferation ability via keeping the Wnt/β-catenin pathway under control." (PMID 35337112, 2022). "A novel molecule known as dorsomorphin has been shown to significantly reduce both mRNA and protein levels of DKK1 in breast cancer cells, suggesting that it could be an effective treatment for breast cancer." (PMID 35355709, 2022). "In contrast, DKK1 expression is downregulated in thyroid cancer, cutaneous squamous cell carcinoma, and breast cancer, suggesting that DKK1 may have a tumour suppressive effect." (PMID 35907982, 2022). "However, it was suggested that DKK1 secreted by perichondrium mesenchymal stem cells inhibited the growth of breast cancer, whereas its absence significantly reduced the inhibitory effects of mesenchymal stem cells on tumor cells." (PMID 35355709, 2022). "Likewise, c-Myc, which is a frequently amplified gene in breast cancers, suppressed DKK1 and transformed human mammary epithelial cells." (PMID 35355709, 2022). "Similarly, in an orthotopically implanted mouse mammary tumor model, DKK1 depletion in 4T1 cells abrogated pulmonary metastases without affecting the local infiltration of the primary tumors." (PMID 35296660, 2022). "Therefore, CBX7 plays a cancer-inhibiting role by guiding the synthesis of DKK-1 to attenuate the Wnt pathway in breast cancer cells." (PMID 34659360, 2021). "CBP/P300 is also involved in the acetylation of the DKK1 promoter in breast cancer." (PMID 34803487, 2021). "Interestingly, in breast cancer, DKK-1 inhibition has contradictory effects depending on the metastatic target tissue." (PMID 34884726, 2021). "Interestingly, both DKK-1 and sFRP4 are antagonists of the Wnt signaling pathway, but the effect of CBX7 in regulating sFRP4 in colon cancer is quite different from the effect of regulating DKK-1 in breast cancer." (PMID 34659360, 2021). "Interestingly, upregulation of DKK1 has shown to be involved in specific breast cancer metastasis to bone." (PMID 34754042, 2021). "Furthermore, Dkk-1 level in the serum of women with breast cancer bone metastases is higher compared with age-matched healthy controls and patients with breast cancer metastases in another site than bones." (PMID 33203195, 2020). "In addition, DKK1, an inducer of bone metastasis and inhibitor of lung metastasis from breast cancer 16, also showed upregulation in BM1 and BM2." (PMID 32792858, 2020).
breast carcinoma (continued). "Additionally, we studied 4 more factors that were pointed out by the cytokine array in the current study, but did not pass all our selection criteria, and appeared in the METABRIC breast cancer database: DKK1, IL-6, LIF, and M-CSF." (PMID 33158447, 2020). "Numerous studies have shown that Dickkopf WNT signaling pathway inhibitor 1 (DKK1), a secreted inhibitor of canonical Wnt signaling and osteoblast differentiation, was implicated in the migration and invasion of HCC, cholangiocarcinoma and breast cancer." (PMID 33708105, 2020). "In addition, Zhuang reported that the DKK1 expression correlates to tumor-secreted DKK1 in breast cancer." (PMID 31830954, 2019). "Some studies have suggested that DKK1 acts as a putative tumor suppressor in breast cancer." (PMID 31285694, 2019). "However, emerging evidences found breast cancer-derived DKK1 inhibits osteoblast differentiation and osteoprotegerin expression which is associated with the presence of bone metastases." (PMID 31285694, 2019). "To determine whether DKK1 could regulate breast cancer cells migration and invasion, we first examined DKK1 expression in 4 different breast carcinoma cell lines (MDA-MB-453, MCF-7, MDA-MB-231 and HCC-1937) using real time PCR and Western blot." (PMID 31285694, 2019). "Consistent with our results, reports from other labs also suggested DKK1 could inhibit migration and invasion of breast cancer cells." (PMID 31285694, 2019). "Mass spectrometric comparison of secreted proteins in breast cancer cell lines known to exhibit bone metastases and lung metastases demonstrated elevated expressions of DKK1 in those with affinity toward bone, and decreased expressions of DKK1 in cell lines with affinity toward lung." (PMID 31698687, 2019). "XAV-939, an inhibitor of β-catenin accumulation could reverse DKK1 silencing-induced MMP7 expression in breast cancer cells." (PMID 31285694, 2019). "The significance of DKK1 expression in breast cancer progression and prognosis remains largely unknown." (PMID 31285694, 2019). "Kang et al12 revealed a complex but sophisticated multi‐genic program mediating breast cancer metastasis to bone, while Zhuang et al13 reported that BCs with high expression of DKK1 are prone to form bone metastases while low expression of DKK1 correlated with lung metastases." (PMID 30575323, 2019). "Knockdown of DKK1 promotes migration and invasion of breast cancer cells." (PMID 31285694, 2019). "DKK1 overexpression dramatically inhibits breast cancer cell migration and invasion." (PMID 31285694, 2019). "DKK1 has been reported to act as a tumor suppressor in breast cancer." (PMID 31285694, 2019). "DKK1 is a secreted protein that plays a crucial role as a negative regulator of the Wnt signaling pathway, and downregulation of DKK1 in colon cancer, breast cancer, hepatocellular carcinoma, and renal cell carcinoma suggests that DKK1 is an antagonist of the Wnt signaling pathway." (PMID 29720122, 2018). "Breast cancer cells frequently secreted Dickkopf-1 (DKK1), a signal transducer in Wnt pathway." (PMID 30597969, 2018). "Here, we investigated whether exercise training causes changes in the serum levels of DKK1 and SFRP1 in patients with breast cancer." (PMID 28178355, 2017). "Furthermore, circulating DKK1 level is consistently increased during bone metastases in patients with breast cancer." (PMID 28178355, 2017). "DKK1 secreted from HUCMSC was found to inhibit breast cancer cell growth." (PMID 28157212, 2017). "However, recent studies have reported that DKK1 is up-regulated in many tumors, including breast cancer, lung cancer, esophageal carcinoma and hepatocellular carcinoma (HCC)." (PMID 27608843, 2016). "It has been reported that DKK1 could down-regulate the expression of β-catenin in breast cancer, thyroid cancer and epidermal neoplasms." (PMID 27608843, 2016).
breast carcinoma (continued). "To further investigate how NBAT1 up-regulated DKK1 via EZH2 in breast cancer, we applied chromatin immunoprecipitation (ChIP)-quantitative real-time PCR (ChIP-qPCR) to analyze trimethylation of histone H3 lysine 27 (H3K27me3) status at DKK1 gene, which is a marker of suppressed chromatin." (PMID 26378045, 2015). "For instance, DKK1 may act as a tumor suppressor through inhibition of Wnt/β-catenin signaling and is reported to activate apoptosis in multiple tumor types e.g breast cancer, renal cell carcinoma, melanoma and choriocarcinoma." (PMID 26353782, 2015). "To analyze whether suppression of DKK-1 is limited to breast cancer cells, we also assessed DKK-1 levels in prostate cancer cells and endothelial cells following exposure to zoledronic acid and atorvastatin." (PMID 24528599, 2014). "Moreover, the potential of breast cancer cells to modulate osteoblastogenesis via DKK-1 was studied in mC2C12 cells." (PMID 24528599, 2014). "Moreover, our data show that breast cancer-derived DKK-1 potently inhibits osteoblast differentiation, as seen assessed by ALP expression, as well as osteoblast-derived production of OPG, a potent inhibitor of osteoclast activity." (PMID 24528599, 2014). "Firstly, the serum levels of DKK-1 in patients with breast cancer was significantly higher than that in healthy individuals, and high serum levels of DKK-1 was found to significantly correlate with TNM stage, tumor grade, lymph node metastasis, and expression of HER2." (PMID 25116444, 2014). "Furthermore, the prognostic role of DKK-1 in breast cancer was evaluated using Cox regression and Kaplan-Meier analysis." (PMID 25116444, 2014). "Considering that serum DKK-1 levels were significantly correlated with TNM stage, tumor grade, and lymph node metastasis, we hypothesized that serum DKK-1 level might affect the prognosis of breast cancer patients." (PMID 25116444, 2014). "DKK1 can be a potential therapeutic target in treatment of metastasis in breast cancer." (PMID 25147739, 2014). "Serum DKK-1 level can be used as a noninvasive biomarker for the prognosis of breast cancer." (PMID 25116444, 2014). "This validated RBM47 as a modulator of DKK1 mRNA level in breast cancer cells." (PMID 24898756, 2014). "Furthermore in cell lines, the ligand Wnt3a increased whilst the inhibitor DKK1 reduced mammosphere formation with the greatest inhibitory effects observed in ER+ve breast cancer cell lines." (PMID 23861811, 2013). "Therefore the tumour-induced osteoblast regulation appears to rely on secreted factors from the cancer cells, further supporting the important role of paracrine molecules such as DKK-1 and Noggin in modulation of osteoblast function by breast cancer cells." (PMID 24069136, 2013). "There is pre-clinical evidence that breast cancer derived DKK-1 inhibits osteoblastogenesis." (PMID 26237142, 2013). "Furthermore, internally truncated form of LRP5 (LRP5Delta) has recently been reported to be resistant to DKK1 inhibition and thus contributes to the activation of Wnt/β-catenin signaling in parathyroid and breast cancer." (PMID 22570728, 2012). "Indeed, DKK1 has been shown to be a secreted tumor suppressor in multiple breast cancer cell lines and is epigenetically silenced in some breast cancer cell lines and primary tumors." (PMID 21952072, 2011). "To verify these model predictions, we treated the MCF-7 cell line and primary breast cancer (BC) cells from 3 patient samples with different concentrations and dosing regimens of Dkk1, and evaluated subsequent formation of mammospheres (MS) and the mammary SC marker CD44+CD24lo." (PMID 21915302, 2011). "Comparatively large Dkk1 concentrations reduced BC-SC numbers down to 25 percent of controls in MCF-7 cells, whereas MCF7 cells differed from primary tumor cells in response to low dose Dkk1, even though these cells were of the same ER+ breast cancer phenotype." (PMID 21915302, 2011).
breast carcinoma (continued). "We postulated that Dkk1 is a QS molecule governing SC fate decision in breast cancer." (PMID 20406437, 2010). "In breast cancer, several genes encoding inhibitors of canonical Wnt/β-catenin signalling have been reported to be frequently hypermethylated, for example, SFRP1, SFRP2, SFRP5, WIF1 and DKK1." (PMID 18826564, 2008). "Additionally, a higher proportion of DKK1 positive tumours was found in advanced breast cancer stages (American Joint Committee on Cancer, TNM stage grouping)." (PMID 17245340, 2007). "Finally, Dkk-1 was measured in the serum of 17 women with breast cancer in complete remission, 19 women with breast cancer and bone metastases, 16 women with breast cancer and metastases at non-bone sites and 16 healthy women." (PMID 17876334, 2007). "Using real-time quantitative RT–PCR and quantitative ELISA, we demonstrated that Dkk-1 was expressed and secreted in large amount only by cultured human breast cancer cell lines (MCF-7, MDA-MB-231, and MDA-B02) known to induce osteolytic bone metastases in mice." (PMID 17876334, 2007). "However, it is also possible that osteolytic breast cancer cells not only secrete pro-osteoclastic factors, but also inhibitors of osteoblast functions including Dkk-1 as suggested by our study." (PMID 17876334, 2007). "Measurements of circulating Dkk-1 levels may be useful for the clinical investigation of patients with breast cancer and bone metastases." (PMID 17876334, 2007). "Moreover, we found high Dkk-1 protein levels in the bone marrow of tumour-bearing legs from mice inoculated with MDA-B02 breast cancer cells." (PMID 17876334, 2007). "Consequently, none of these in vitro studies correlate with the clinical observation we report here, about the presence of DKK1 protein in growing tumours from breast cancer patients." (PMID 17245340, 2007). "The expression of Dkk-1 in human breast cancer cell lines was analysed by RT–PCR." (PMID 17876334, 2007). "Importantly, DKK1 protein production was confirmed in multiple breast cancer specimens that were positive by RT–PCR." (PMID 17245340, 2007). "Here, we report the expression of Dickkopf-1 (DKK1) in breast cancer and other tumours." (PMID 17245340, 2007). "Additional mechanisms, such as the stimulation by bone-residing breast cancer cells of Dkk-1 expression by bone marrow cells, may also be involved in the high local production of Dkk-1." (PMID 17876334, 2007). "Importantly, DKK1 protein production was evaluated by ELISA in crude extracts prepared from breast cancer clinical specimens." (PMID 17245340, 2007). "Finally, we observed substantial DKK1 protein secretion in breast cancer lines, which was further confirmed in crude extracts prepared from breast cancer specimens." (PMID 17245340, 2007). "Interestingly, by analysing its expression profile in breast cancer patients, DKK1 appears in tumours with a poor outcome, specifically hormone-independent cases." (PMID 17245340, 2007). "Only breast cancer cells that induce osteolytic lesions in animals produced Dkk-1." (PMID 17876334, 2007). "Similarly, in breast cancer, the overexpression of prostate tumor overexpressed-1 has been found to inhibit DKK1 transcription through the recruitment of histone deacetylase 1(HDAC1) and HDAC2, resulting in decreased levels of histone H3/H4 acetylation at the DKK1 promoter." (PMID 38886806, 2024). "Thus, targeting DKK1 in breast cancer could offer multiple therapeutic benefits from increasing anti-tumor immunity via unleashing NK cell suppression from the tumor microenvironment to targeting disseminated tumor cells and/or cancer stem cells." (PMID 38659818, 2024). "MSCs have been reported to inhibit tumor progression via various paracrine factors in hepatocellular carcinoma, breast cancer, ovarian cancer, and glioma, these factors include insulin-like growth factor-binding protein 3, transforming growth factor-β and DKK1." (PMID 37287079, 2023).